CTF1 (cardiotrophin 1)
Diseases named in the same sentence as CTF1 in open-access papers:
CTF1 is named in the same sentence as 66 diseases in open-access papers, as found by Europe PMC text mining. Sharing a sentence is not in itself a finding about the gene and the disease. The quoted sentences say what the papers report.
cardiac hypertrophy (6 papers, 2013 to 2024). "Antisense ODNs directed against leukemia inhibitory factor (LIF) and cardiotrophin-1 were successful in downregulating angiotensin II-induced cardiac hypertrophy in vitro." (PMID 34089101, 2021). "Cardiotrophin-1 (CT-1) is a gp130 ligand and a member of the interleukin- (IL-) 6 family, originally described as an active inducer of cardiac hypertrophy, atherosclerosis and, thus, a potential appropriate example of DAMP." (PMID 23690661, 2013). "Jak-Stat Signaling: IL-6 pathway is activated in response to the IL-6 family of cytokines (IL-6, cardiotrophin 1, and leukemia inhibitor factor), cross-talks with the EGFR pathway, and is involved in cardiac hypertrophy." (PMID 36380187, 2022). "Cardiotrophin-1, activin A, insulin-like growth factor binding protein-7 (IGFBP-7) and Heart fatty-acid binding protein have demonstrated a stable positive correlation with cardiac hypertrophy, contractibility and steatosis responses." (PMID 28231848, 2017).
atherosclerosis (4 papers, 2013 to 2020). A disease characterized by the build-up of fatty material and calcium deposition in the arterial wall resulting in partial or complete occlusion of the arterial lumen. "Cardiotrophin-1 (CT-1), a member of interleukin-6-type proinflammatory cytokines, has potent cardiovascular actions and is highly expressed in vascular endothelium, however its role in atherosclerosis has not been fully elucidated to date." (PMID 23935888, 2013).
diabetes (4 papers, 2014 to 2017). "Our previous study showed that subjects with impaired glucose tolerance and diabetes had significantly higher cardiotrophin-1 concentrations than those with normal glucose tolerance, and impaired glucose tolerance and diabetes were positively associated with cardiotrophin-111." (PMID 26621340, 2015). "For this reason, and because of its high expression in tissues that play a pivotal role in the pathogenesis of type 2 diabetes like beta-cells, skeletal muscle and liver, the CT-1 gene (CTF1) would be a promising candidate to associate with diabetes, insulin secretion and insulin sensitivity." (PMID 25025664, 2014). "Recently, cardiotrophin-1, a member of the interleukin-6 family of cytokines was described to protect beta-cells from apoptosis, to improve glucose-stimulated insulin secretion and insulin resistance, and to prevent streptozotocin-induced diabetes in mice." (PMID 25025664, 2014). "Therefore, in the current work we excluded subjects with diabetes to minimize the positive effect of hyperglycemia on cardiotrophin-1, and the results showed that cardiotrophin-1 is inversely associated with BMI, or being overweight and obese, in non-diabetic individuals." (PMID 26621340, 2015). "This review focuses on the effects of omentin, vaspin, cardiotrophin-1, Tumor necrosis factor-like Weak Inducer of Apoptosis (TWEAK) and nephroblastoma overexpressed (NOV/CCN3) on obesity and diabetes." (PMID 28809783, 2017). "The aim of this study is thus to investigate the relationships among cardiotrophin-1 levels, overweight and obese individuals without diabetes in a Chinese population." (PMID 26621340, 2015). "Therefore, the aim of this study was to investigate the relationships among cardiotrophin-1 levels, overweight and obese individuals without diabetes in a Chinese population." (PMID 26621340, 2015).
Hypertension (4 papers, 2014 to 2022). The presence of chronic increased pressure in the systemic arterial system. "Moreover, concordant effects on high blood pressure were found at three loci, including SH2B3, CTF1 and HDAC7, consistent with the epidemiologic association of high blood pressure with increased IgA levels." (PMID 36369178, 2022).
heart failure (3 papers, 2017 to 2024). Inability of the heart to pump blood at an adequate rate to meet tissue metabolic requirements. "Increased expression levels of RNA and CTF1 protein were observed in failing left ventricular myocardium, pointing to a contributory role in heart failure." (PMID 39337275, 2024). "Cardiotrophin-1 (CT-1) is a gp130 cytokine that was previously characterized for its effects on cardiomyocytes and identified as a marker of heart failure." (PMID 31013924, 2019). "Cardiotrophin 1 (CT1) was originally identified as a promising hypertrophic agonist in vitro, however its expression has been more recently linked to myocardial pathology, systemic elevated blood pressure, and cardiac failure in both animals and humans." (PMID 28785017, 2017).
Obesity (3 papers, 2015 to 2023). Accumulation of substantial excess body fat. "In conclusion, this study provided epidemiological evidence that non-diabetic subjects who were overweight or obesity had significantly lower cardiotrophin-1 concentrations than those with normal weight, and both obesity and being overweight were inversely associated with cardiotrophin-1 levels." (PMID 26621340, 2015). "However, the mechanisms underlying the role of cardiotrophin-1 in obesity are unclear." (PMID 26621340, 2015). "Moreover, both obesity and being overweight were inversely associated with cardiotrophin-1." (PMID 26621340, 2015). "Cardiotrophin-1 null mice develop obesity and recombinant cardiotrophin-1 treatment reduces body weight in ob/ob and in high-fat-fed obese mice." (PMID 26621340, 2015). "Obesity may thus exert an inhibitory feedback pathway through the activation of SOCS to downregulate the expression of cardiotrophin-1." (PMID 26621340, 2015). "Our data suggest that increased bodyweight might be related to the reduced cardiotrophin-1 status, and support the view that cardiotrophin-1 may be a promising therapy for obesity." (PMID 26621340, 2015). "In addition, we found that obese, diabetic subjects had significantly lower cardiotrophin-1 levels than non-obese diabetic patients, and obesity was negatively associated with cardiotrophin-111." (PMID 26621340, 2015). "The results of this study provided epidemiological evidence that non-diabetic subjects who were overweight or obesity had significantly lower cardiotrophin-1 concentrations than those with normal weight, and both obesity and being overweight were inversely associated with cardiotrophin-1 levels." (PMID 26621340, 2015). "Whether these inflammatory cytokines played a role in the relationship between cardiotrophin-1 and obesity could not be determined." (PMID 26621340, 2015).
type 2 diabetes (3 papers, 2013 to 2020). "This study indicates that exercise training, despite the type, is an efficient method to modify apelin, APJ receptor, NO, and cardiotrophin-1 values in animals with type 2 diabetes." (PMID 32908933, 2020). "Our study also revealed that CREB binding protein (CREBBP) and cardiotrophin-1 (CTF1) have suggestive roles in linking Type 2 diabetes and neuromuscular diseases." (PMID 23776558, 2013).
Alzheimer disease (2 papers, 2023 to 2025). A progressive, neurodegenerative disease characterized by loss of function and death of nerve cells in several areas of the brain leading to loss of cognitive function such as memory and language. "Elevated levels of plasma CTF1 were genetically associated with an increased risk of CRC, as well as a stronger predisposition to various mental disorders, including such as Alzheimer’s disease, dementia, delirium, dementia and amnestic disorders, and other cognitive disorders." (PMID 38049731, 2023).
breast carcinoma (2 papers, 2023). "Moreover, higher levels of CTF1 expression in breast cancer tissues were associated with significantly higher rates of lymph node metastasis in patients." (PMID 38234683, 2023). "CTF1 expression is increased in breast cancer tissues and is associated with lymph node metastasis." (PMID 36831154, 2023). "This indicates that CTF1 and autophagy are involved in breast cancer cell migration and invasion by interaction with CAF." (PMID 36831154, 2023). "Furthermore, CTF1-induced stromal autophagy was necessary to facilitate migration and invasion of breast cancer cells." (PMID 38234683, 2023).
colon cancer (2 papers, 2021 to 2022). "Surprisingly, in view of the very different cell types, we found that US7 cells with ST6Gal1 overexpression had 19 genes in common (18 increased and one decreased) with the SW948 ST6Gal1 overexpressing colon cancer cells, including, among others, ST6GAL1, TGFβ2, and CTF1." (PMID 35371997, 2022).
hypertensive heart disease (2 papers, 2022 to 2023). Abnormal enlargement of the heart resulting from long-standing hypertension. "The CTF1 gene encodes a secretory cytokine capable of inducing cardiomyocyte hypertrophy in vitro, and it plays roles in hypertensive heart disease, dilated cardiomyopathy, lung adenocarcinoma and other diseases." (PMID 35574315, 2022).
metabolic syndrome (2 papers, 2013 to 2015). A cluster of metabolic risk factors for CARDIOVASCULAR DISEASES and TYPE 2 DIABETES MELLITUS. "Cardiotrophin-1 (CT-1), a newly discovered member of the IL-6 family and a key regulator of metabolism were also reported to be upregulated in metabolic syndrome." (PMID 23365487, 2013).
acne (1 paper, 2026). An inflammatory process of the sebaceous glands which is characterized by comedones, nodules, papules and/or pustules on the skin. "RESULTS: Serum IL-17 and cardiotrophin-1 levels were significantly higher in the acne group compared to controls (p < 0.001)." (PMID 41733892, 2026). "A positive correlation was found between IL-17 and cardiotrophin-1 (r = 0.549, p < 0.001), and both were correlated with acne severity (cardiotrophin-1: r = 0.735; IL-17: r = 0.453; p < 0.001)." (PMID 41733892, 2026). "CONCLUSIONS: The elevated levels of IL-17 and cardiotrophin-1 and their correlation with disease severity suggest their potential role as inflammatory biomarkers in acne." (PMID 41733892, 2026). "Interleukin-17 (IL-17) and cardiotrophin-1, two mediators involved in inflammation and metabolic stress, have been proposed as potential contributors to acne pathophysiology." (PMID 41733892, 2026). "This study aimed to compare serum IL-17 and cardiotrophin-1 levels between acne patients and healthy controls and to assess their relationship with disease severity." (PMID 41733892, 2026).
bladder cancer (1 paper, 2024). "We first demonstrated, in invasive T24 bladder cancer cells, that N-cadherin was cleaved by ADAM10 generating NTF in the extracellular environment and leaving a membrane-anchored CTF1 fragment and that Tspan15 is required for ADAM10 to induce the selective N-cadherin cleavage." (PMID 38667323, 2024).
brain cancer (1 paper, 2023). A primary or metastatic malignant neoplasm affecting the brain. "This is a gene-rich region and we also identified GWS gene associations at this locus with FBXL19, BCL7C and CTF1, all three genes being reasonable candidates with putative roles in neuronal development, neuronal degeneration and/or brain cancer." (PMID 36940203, 2023).
Chronic heart failure (1 paper, 2009). "Chronic heart failure (CHF) is associated with elevated concentrations of tumor necrosis factor (TNF) α and cardiotrophin-1 (CT-1) and altered peripheral blood mononuclear cell (PBMC) function." (PMID 20224758, 2009).
colitis (1 paper, 2019). Inflammation of the colon. "In the present study, we assessed the utility of cardiotrophin-1 (CT-1) in an experimental model of dextran sulfate sodium (DSS)-induced colitis in mice." (PMID 31805674, 2019).
glycogen-storage cardiomyopathy (1 paper, 2019). "PRKAG2 is associated with glycogen-storage cardiomyopathy and CTF1 induces cardiac myocyte hypertrophy in vitro." (PMID 30732658, 2019).
Hepatic steatosis (1 paper, 2021). Steatosis is a term used to denote lipid accumulation within hepatocytes. "Cardiotrophin-1 resolves hepatic steatosis in obese mice by mechanisms involving AMPK activation." (PMID 33647884, 2021).
Hyperglycemia (1 paper, 2015). An increased concentration of glucose in the blood. "However, there are currently no studies on cardiotrophin-1 in obese subjects without hyperglycemia." (PMID 26621340, 2015).
hyperlipidemia (1 paper, 2023). "Furthermore, heightened levels of CTF1 were linked to an increased risk of developing metabolic issues such as hyperlipidemia and disorders of lipid metabolism." (PMID 38049731, 2023).
ischemic heart disease (1 paper, 2022). "Ian Dixon’s laboratory has studied a member of the IL-6 family of cytokines, cardiotrophin-1 (CT-1), which is increased in the serum of patients suffering from ischemic heart disease." (PMID 35892569, 2022).
left ventricular hypertrophy (1 paper, 2016). Enlargement of the LEFT VENTRICLE of the heart. "Cardiotrophin-1, a member of the interleukin-6 cytokine family that signals through the cytokine receptor gp130, is associated with left ventricular hypertrophy and failure." (PMID 27936050, 2016).
leukaemia (1 paper, 2022). "After GO analysis of the seventy-four genes, six secreted cytokines related to cell cycle, proliferation and apoptosis including CSF2, CTF1, FGF2, IGF2, HGF and LIF were selected for PCR verification and FGF2 was confirmed to be significantly up-regulated in leukaemia mice derived MSCs." (PMID 36333298, 2022).
lymph node metastasis (1 paper, 2023). "CTF1-related autophagy and CAF activation supported cancer cell migration and invasion in vitro and correlated with lymph node metastasis in patient-derived tissue samples." (PMID 38234683, 2023).
malaria (1 paper, 2025). Malaria is a serious and sometimes fatal disease caused by a parasite that commonly infects a certain type of mosquito which feeds on humans. "The expression of Osm, Lif, Ctf1, and Lifr were sensitive to both malaria and vaccination." (PMID 40243929, 2025).
renal fibrosis (1 paper, 2013). A final common manifestation of a wide variety of chronic kidney diseases characterized by glomerulosclerosis and tubulointerstitial fibrosis. "Another study defining the role of cytokine cardiotrophin 1, in cardiac, vascular, and renal function found increased renal fibrosis with cardiotrophin 1 infusion which was associated with a decreased MMP-13/TIMP-1 ratio suggesting a protective role in this model." (PMID 24159376, 2013).
cancer (6 papers, 2021 to 2024). A tumor composed of atypical neoplastic, often pleomorphic cells that invade other tissues. "Cancer-derived CTF1 triggered STAT3 phosphorylation and nuclear translocation, initiating transcriptional activation of essential autophagy genes." (PMID 38234683, 2023). "Similar to TGF-β, cancer cell-derived CTF1 alone induced CAF phenotype demonstrated by α-SMA and vimentin upregulation, actin stress fiber formation and enhanced contractile properties in fibroblasts." (PMID 38234683, 2023). "Cardiotrophin 1 (CTF1) derived from cancer cells was reported to induce protective autophagy by activating AMPK in fibroblasts from tumor stroma." (PMID 36677797, 2023). "Therefore, the anticancer effect of CTF1 identified in our study suggests that this molecule may have a role in the field of cancer treatment." (PMID 33782686, 2021). "Interestingly, the expression levels of four genes (PDGFB, CCND2, CTF1, IL7R) identified in the current study were strongly associated with STAT3 activation, clinical outcome of LUAD patients and drugs sensitivity across cancer cell lines in GDSC." (PMID 34301211, 2021). "Studies have identified several factors e.g., ROS, CTF1, TGF-β that were derived from cancer cells and leading the activation of autophagy in the stroma." (PMID 38234683, 2023). "Hence, CTF1 was a novel component of cancer-TME crosstalk and an inducer of autophagy-dependent CAF formation and cancer metastasis." (PMID 38234683, 2023). "Cardiotrophin‐1 (CTF1) is a type of interleukin‐6 that has well‐established protective and hypertrophic actions towards cardiac myocytes, but the connection between CTF1 and cancer is still not well‐explored." (PMID 38804848, 2024).
tumor (6 papers, 2021 to 2024). "Given how CTF1 functions, it is hypothesized to reduce the cardiotoxicity of tumor sufferers after treatment and protect other organs such as the liver, kidney, or nervous system." (PMID 38804848, 2024). "CTF1 and RAPGEF3 were previously reported to be parts of gene signatures related to tumor microenvironment and immune system, with the first seen downregulated and methylated in BAP1 mutated samples; PALMD was found to have low expression in metastatic UM tissues, and GSTA3 in low-survival patients." (PMID 38339073, 2024).
infection (5 papers, 2016 to 2025). The state of being infected such as from the introduction of a foreign agent such as serum, vaccine, antigenic substance or organism. "We now compared the gene sets differentially expressed in the SGE1, aTF1 and cTF1 overexpressors and during infection." (PMID 27855160, 2016). "Given that expression levels of SGE1, aTF1 and cTF1 increase during infection, we assume that strains overexpressing either of these transcription factor genes partially mimic the in planta state." (PMID 27855160, 2016). "Among the IL-6 family members, significant changes (p-value < 0.05) were found for Ctf1, whose constitutive mRNA level was reduced by vaccination per se, and remained lower upon malaria infection compared to in unvaccinated mice, but only for the first 4 days of infection." (PMID 40243929, 2025). "Both aTf1 and cTf1 up-regulate expression of the shorter aTF1 gene on the pathogenicity chromosome (FOXG_16414), although not to the same level as during infection." (PMID 27855160, 2016).
cardiovascular disease (1 paper, 2022). "CTF1 is a procardiogenic factor that has been shown to play important roles in cardiovascular disease." (PMID 36204584, 2022).
degenerative diseases (1 paper, 2025). "In recent years, biomarkers, such as Galectin-3 and Cardiotrophin-1, have been investigated in inflammatory and degenerative diseases." (PMID 40431592, 2025). "In recent years, biomarkers such as Galectin-3 and Cardiotrophin-1 have been studied in inflammatory and degenerative diseases." (PMID 40431592, 2025).
kidney diseases (1 paper, 2022). "Other detected genes including SLC19A3, CTF1, and GATM are related to kidney diseases." (PMID 35464862, 2022).
neurological disease (1 paper, 2025). "Also, 59 unique proteins were associated with AD, and 10 of them (17%) showed an association with AD and an additional neurological disease (CTF1, NSF and PRSS53 with PD; SIGLEC9 with ALS; CR1, CTSH, PARP1 and PVR with MS; LRRC37A2 with both PD and ALS; and IDUA with PD, ALS and MS)." (PMID 40037332, 2025).
CTF1 also shares sentences with these, for which no sentence is quoted: dementia (2 papers); Insulin resistance (2); Non-Alcoholic Fatty Liver Disease (2); amnestic disorder (1); amyotrophic lateral sclerosis (1); cognitive disorder (1); delirium (1); dengue (1); diabetic nephropathy (1); dilated cardiomyopathy (1); epilepsy (1); Fabry disease (1); immune disorders (1); Impaired glucose tolerance (1); liver cirrhosis (1); lung adenocarcinoma (1); lung carcinoma (1); lupus nephritis (1); membranous glomerulonephropathy (1); mental disorder (1); minimal change disease (1); multiple sclerosis (1); nasopharyngeal carcinoma (1); neuromuscular disease (1); Obstructive Sleep Apnea (1); pancreatitis (1); Parkinson disease (1); psoriasis (1); retinal degeneration (1); steatosis (1).
A further 2 diseases each share a sentence with CTF1 in 1 paper.